RAG1 (recombination activating 1)
Diseases named in the same sentence as RAG1 in open-access papers (continued):
Sharing a sentence is not in itself a finding about the gene and the disease.
tumor (continued). "Next, to prove that the more efficient killing of DENR KO tumors over WT tumors was indeed due to increased tumor infiltration and enhanced killing of CD8+ T cells, we subcutaneously implanted DENR KO and control cells into the flanks of RAG1−/− mice in which the T cells and B cells were depleted." (PMID 35440133, 2022). "In our classification, RAG-1 is enriched in STK11/LKB1 mutants, suggesting that this tumour group could be refractory to immune checkpoint blockade (ICB)." (PMID 36163168, 2022). "The therapeutic effect of PD-1–laIL-2 was totally abolished in Rag1–/– mice, which suggests that NK cells are not sufficient for PD-1–laIL-2–induced tumor control and that T cells are required for the therapeutic function of PD-1–laIL-2." (PMID 35104810, 2022). "Further transcutaneously delivered nor-NOHA did not induce a significant reduction of tumor growth in vivo in Rag1 KO mice." (PMID 34031449, 2021). "Furthermore, the adaptive immune compartment was necessary for the protection against tumor growth, as B16F10 tumors grew at similar rates in FL-treated Rag1–/– and Rag1–/–Clec9agfp/gfp mice." (PMID 33980589, 2021). "We have previously generated transgenic mice expressing the human inhibitory receptor KIR2DL3 (TgKIR mice), which were crossed with RAG-1 KO animals that lack T and B cells (TgKIR-RAG1KO) to generate recipients for human tumor cells expressing the MHC class I molecule HLA-Cw3, a ligand for KIR2DL3." (PMID 34071607, 2021). "Early control of Ptgs−/− tumors was still noticeable in Rag1−/− mice lacking adaptive immunity, arguing for direct NK cell cytotoxic activity against Ptgs−/− tumor cells." (PMID 33220234, 2020). "Recipient mice that received cells from donors treated with STAT3 inhibitor displayed impaired tumor growth compared to both mice that receive lymphocytes from control tumor-bearing mice or non-reconstituted RAG1-/- mice." (PMID 33330068, 2020). "This also demonstrated that the tumor size reduction that was present in the TRAMPfmsmic-1 cohort was abolished in the TRAMPfmsmic/rag1-/- group that overexpressed GDF15 but also lacked adaptive immunity." (PMID 32502202, 2020). "To evaluate the role of Blimp-1 on CD4-driven tumor control, we isolated CD4+ TILs from MCA205 tumors and dLNs from αCTLA-4-treated Prdm1fl/fl or Prdm1−/−Cd4cre mice and transferred them to MCA205-bearing Rag1−/− mice." (PMID 31924474, 2020). "The improved survival and reduced tumor size that is seen in GDF15 overexpressing TRAMPfmsmic mice is completely abrogated in triple transgenic TRAMPfmsmic/rag-/- mice, that also lack adaptive immunity because of deletion of the Rag1 gene." (PMID 32502202, 2020). "To test this, we established YMR1.7 tumor in RAG1−/− mice (lack of T cells and B cells) and i.t. treated them with SLR14 or vehicle." (PMID 31601678, 2019). "(A) A schematic diagram of tumor inoculation, drug treatment and CTL transfer in RAG1 KO mice." (PMID 31511064, 2019). "After the tumor was well established (about 100 mm3), a total of 2 × 106 lymph node (LN) cells from OTI transgenic mice were transferred into tumor-bearing Rag1−/− mice to reconstitute a small number of T cells without reducing tumor growth." (PMID 31324798, 2019). "This was a reasonable hypothesis, since we have observed that antigen presenting cells in RAG1-/- mice could be activated by injection of anti-CD40 and activate transferred T lymphocytes from tumor bearing donors." (PMID 29975708, 2018). "We then focused our analysis on the tumor samples taken at the same time point, day 23, for wild-type and RAG1−/− samples and considered neoantigens found both in the MC38 cell line and in at least one of the RAG1−/− tumors." (PMID 29296022, 2018). "Here, we present in vivo evidence, that the combined absence of Aid and Rag1 in tumor prone murine pro-B cells accelerates pro-B ALL incidence, which suggests a functional role of Aid in Rag1 deficient BM pro-B-cells even before the expression of a pre-BCR." (PMID 29100269, 2017).
tumor (continued). "RAG1 transcripts are not produced by human ALCL tumours (even though RAG2 transcripts are detectable in our murine NA/OTI tumours)." (PMID 26753883, 2016). "Accordingly, RAG1-/- mice bearing established subcutaneous B16-F10 tumors were injected intratumorally (i.t.)with vMyx-IL15Rα-tdTr, vMyx-tdTr or PBS on days 7 and 10 post tumor cell injection." (PMID 25329832, 2014). "Even in this situation, the proliferation of OTI or OTII cells was not improved, suggesting the presentation of tumor antigen in the draining LN was similar in RAG1−/− hosts and C57BL/6 mice." (PMID 21390236, 2011). "TIDC phenotype in RAG1−/− mice was not significantly affected by the transfer of purified CD8+ T cells or CD4+CD25+ Treg one day before tumor inoculation (data not shown)." (PMID 21390236, 2011). "Although we did not see full protection with DTA-1 in this RAG1−/− reconstitution system, there was a statistically significant delay in tumor growth seen only when both Teff and Treg were GITR +/+." (PMID 20454651, 2010). "We then transplanted the transduced tumor cells into Rag-1–/– mice, to evaluate tumor fitness in the absence of any T cell responses to the reporter genes." (PMID 18578569, 2008). "To determine whether CQ-mediated tumor suppression is T-cell-dependent or not, we designed an experiment in which CQ treatment is given to RAG1−/− mice." (PMID 39247196, 2024). "Notably, such treatments reduced tumour growth and weight in wild-type mice challenged with MC38 or B16-OVA tumour cells but not in Rag1–/– mice, suggesting the importance of adaptive immunity in mediating the anti-tumour effect of glutamine." (PMID 37407815, 2023). "Non-adaptive immune mechanisms such as macrophage or NK cell recognition have been shown to clear senescent tumor cells, but given that we see no tumor-suppressive effect in Rag1−/− mice that have macrophages and NK cells, we do not believe there is an obvious role for NK cells in our tumor models." (PMID 35017504, 2022). "ACPP-MMAE or IR monotherapy had similar tumor growth curves and mouse survival irrespective of whether tumors were grown in RAG1 KO or WT genetic backgrounds." (PMID 35790753, 2022). "To test this hypothesis, we first demonstrated that the protective effects of ONP-302 were dependent on a functional adaptive immune system as no delay in tumor growth was seen in treated Rag1-/- mice." (PMID 36059473, 2022). "Interestingly, the rate of invasive tumor occurrence in Apc/Dok3 mice lacking Rag1 (26%) was significantly lower than that in Apc/Dok3 mice (56%)." (PMID 36970719, 2022). "To examine whether IFNγR1KO affected tumor formation in vivo, we inoculated Rag-1−/− mice lacking mature T and B cells with scrambled control and IFNγR1KO cells." (PMID 36008408, 2022). "However and in direct contrast to the durable tumor control seen of MMAE-radiosensitized tumors in WT mice, ACPP-MMAE together with IR did not appreciably increase tumor control in RAG1 KO mice compared to IR alone." (PMID 35790753, 2022). "Notably, the protective effect of non-antigen-specific IgA disappeared in both RAG1-deficient and NSG mice and tumour-derived TSPAN7 and BDNF antibodies showed decreased anti-tumour effects, consistent with the capacity to transcytose through tumour cells." (PMID 33536615, 2021). "Consequently, the tumor sizes were less than 160 mm2 on day 28 post-B16F10-OVA injection, while those in the control (Rag1-/- transplanted with B16F10-OVA) group were around 400 mm2 on day 22 postinjection, leading to euthanasia to comply with experimental animal ethics procedures." (PMID 32669292, 2020). "However, NK cells in Rag1-deficient mice display hyperresponsiveness, and depletion of CD8+ T cells, but not NK cells, negates IL-15C-mediated tumor clearance." (PMID 31552035, 2019).
tumor (continued). "In addition, antibody-mediated depletion of NK cells in WT or Rag1−/− mice resulted in a decrease in cDC1 within Ptgs1/Ptgs2−/− BRAFV600E tumors irrespective of total tumor mass." (PMID 29429633, 2018). "The transfer of activated MHC-II-/- B lymphocytes with T lymphocytes from tumor bearing donors could not inhibit tumor growth in RAG1-/- mice, indicating that the control of tumor growth was dependent on antigen presentation by the B lymphocytes." (PMID 29975708, 2018). "In order to explore the physiological relevance of Aid at the pro-B cell stage, and independent of Rag1 off-target activity, we designed a mouse model which allows the investigation of an arrested tumor-prone pro-B cell population in combination with Aid deficiency." (PMID 29100269, 2017). "However, the data presented herein using B16 tumours grown in Rag1-/- mice, suggests neither antibodies (nor T cells) play a major role in reducing relapse rates." (PMID 27100888, 2016). "Therefore, we reconstituted RAG1−/− mice with different combinations of Teffs and Tregs isolated from either GITR−/− or GITR+/+ littermates, challenged with B16, and treated with DTA-1 or IgG on day 4 of tumor growth." (PMID 20454651, 2010). "DHCR24 promotes tumor proliferation, apoptosis resistance, and invasion through cholesterol biosynthesis, and activates the PI3K‐AKT signaling pathway, while RAG1, reexpressed by tumor‐infiltrating T cells—may facilitate immune evasion via TCR specificity remodeling." (PMID 40784724, 2025). "To specifically determine the extent to which the induction of anti-tumor activity by Compound 182 may be reliant on targeting PTP1B and/or PTPN2 in T cells, we next asked if Compound 182 could repress the growth of AT3-OVA tumors in Rag1–/– (C57BL/6) mice that lack T cells and B cells." (PMID 37500611, 2023). "The growth of PDV tumors in immunodeficient Rag1 knockout (KO) mice (B6.129S7-Rag1tm1Mom/J) in contrast to the immunocompetent B6 mice demonstrates that PDV tumors are immunologically rejected in B6 mice; furthermore, PDVC57 tumors may modulate the immune microenvironment to promote tumor growth." (PMID 34031449, 2021). "To evaluate whether ongoing recombinase activity could occur in established ALK+ ALCL tumours, we looked for RAG1 transcripts in 52 cases, but all were negative, as were all the three ALCL cell lines tested in contrast to the immature T-ALL cell lines arrested at a thymic stage of development." (PMID 26753883, 2016). "To investigate the role of CD4+ T cells in TSLP-mediated tumor protection, we transferred naïve CD4+ T cells from WT mice into Rag1–/– (Rag1KO) mice with or without TSLP overexpression." (PMID 39744942, 2025). "We found that CQ treatment was not effective in suppressing the tumor mass in RAG1−/− mice; however, in C57BL/6 mice, CQ treatment effectively suppressed tumor mass." (PMID 39247196, 2024). "We found that MDP treatment reduced the metastatic colonization of B16F10 cells in Rag1–/– but not NOD/SCID mice, suggesting that T and B lymphocytes are dispensable for the tumor immunity mediated by I-NCMs." (PMID 39545417, 2024). "In contrast to the significantly increased tumor burden in Chatfl/fl; Cd4-cre mice, HCC progression was not exacerbated in Rag1–/– mice but instead was alleviated." (PMID 37640929, 2023). "In Rag1−/− mice co-transplanted with RAMP1-expressing and -non-expressing CD8+ T cells, we found that within the same tumour, the relative proportion of intratumoral PD-1+LAG3+TIM3+ CD8+ T cells was lower in Ramp1−/− CD8+ T cells." (PMID 36323780, 2022). "Relapse rates were not significantly different between Rag1-/- and C57BL/6 mice, suggesting neither B nor T cells play a major role in the anti-tumour efficiency of ingenol mebutate in the B16 model." (PMID 27100888, 2016).
tumor (continued). "Another interesting finding is that depletion of RAG1 or RAG2 elicits T-ALL cell growth inhibition (data not shown), suggesting that these recombination activation genes may have other tumor-promoting roles in cells already transformed." (PMID 34322489, 2021). "In our experimental model, we have shown that very small tumors in RAG1-/- mice did not affect APCs, since a single injection of anti-CD40, together with T cell transfer from tumor bearing donors, could protect mice from tumor growth." (PMID 29975708, 2018). "Indeed, anti-CD40 treated DCs isolated from donors with TC-1 tumors could not inhibit tumor growth in RAG1-/- mice when transplanted with T cells, differently from what we observed with the B lymphocytes, which suggested that these cells were more resistant to the effects of the tumor." (PMID 29975708, 2018). "Moreover, thymic lymphoblastic lymphomas were never observed in FADD-/- RAG-1+/+ or FADD-/- RAG-1+/- mice, demonstrating that absence of FADD expression was necessary but not sufficient to induce tumor development in this model." (PMID 15717929, 2005). "To determine whether the effects of RFWD3 on tumor growth are immune‐dependent or not, we subcutaneously inoculated shNC‐ or shRfwd3‐transfected LLC cells into NOD/ShiLtJGpt‐Prkdcem26Cd52Il2rgem26Cd22/Gpt (NSG) mice or Recombination‐Activating Gene 1 (Rag1) KO mice." (PMID 41117130, 2025).
infection (175 papers, 2008 to 2026). The state of being infected such as from the introduction of a foreign agent such as serum, vaccine, antigenic substance or organism. "Like the immune-competent mice, Rag1−/− PEP-R619W mice had noticeably less weight loss throughout most of the early stages of the infection and mice survived longer compared to Rag1−/− PEP-WT mice at both 5e4 and 1e5 PFU MHV A59 infection." (PMID 40791464, 2025). "IFNγ- and Rag1- deficient mice both showed a 100% mortality rate by 64- and 93-days post infection, respectively, demonstrating that type 1 immunity and adaptive lymphocytes in general are required for protection." (PMID 40568097, 2025). "Under GF condition, infection of CR in both Rag1-/- and Il22-/- mice is sufficient to cause severe symptoms and mortality, supporting that CR indeed harbors gut microbiota-independent virulence." (PMID 39630719, 2024). "Next, we used immunocompromised (Rag-1-deficient) mice, to identify immunologic cascades essential for controlling infection." (PMID 38198478, 2024). "In contrast, infection of αβ T cell KO mice (Tcrb−/−) resulted in a susceptibility phenotype virtually identical to that of the Rag1 KO animals." (PMID 39440975, 2024). "One of the limitations of the mouse model of leprosy infectionis that infections cannot be established in immunocompetent mice;28,37 therefore, the role of Mincle was investigated in this study ona Rag1-deficient background, which lacks acquired immunity." (PMID 37521780, 2023). "We observed that parasite elimination was incomplete in cKO mice on day 21 post infection with similar worm counts as susceptible Rag1-/- mice, at which point nearly all WT littermates had cleared the infection." (PMID 33788902, 2021). "To determine the contribution of these responses to recovery from MA-CCHFV infection, we infected 8-week-old WT or B- and T-cell-deficient Rag1-/- mice with MA-CCHFV." (PMID 33416494, 2021). "Conversely, at 7 days post infection, while NSG mice were still more susceptible to infection, in agreement with published data, Rag1–/– mice appeared more resistant, as shown by improved histopathology and a trend towards a reduced fungal burden." (PMID 34445184, 2021). "S. ratti clearance was significantly impaired in RAG1-deficient mice that lack both T and B cells, as evidenced by continued fecal egg deposition and presence of intestinal worms up to 25 days post-infection." (PMID 34237106, 2021). "To determine if natural antibody can promote immunity in our model, we measured alveolar macrophage phagocytosis of C. neoformans in Rag1−/− mice treated with naive wild-type IgM-sufficient or sIgM−/− IgM-deficient sera before infection." (PMID 28837391, 2018). "Remarkably, the role of lamin A/C in viral clearance seems to be CD4+ T-cell dependent, since only CD4+ T-cells were adoptively transferred to T- and B-cell-deficient Rag1−/− mice before mouse infection with VACV." (PMID 29311549, 2018). "In previous studies, we identified mutations in nsP1 that attenuated RRV-T48 infection in WT and Rag1-/- mice." (PMID 29244871, 2017). "Dynamic disease progression among rag1 (−/−) fish was associated with elevated mycobacterial loads compared to wt controls during the first weeks of infection." (PMID 23028333, 2012). "B and T cell-deficient Rag1−/− mice succumb to B. bronchiseptica infection, and death is associated with systemic spread of the infection." (PMID 22897969, 2012). "In association, previous studies have shown the importance of IFNγ-producing CD4+ T-cells in increasing resistance of RAG-1/IFNγ-double-deficient mice against an infection with C. pneumoniae." (PMID 22096480, 2011). "Infection of WT, RAG-1−/−, or MyD88−/− mice resulted in weight loss beginning at day 2 post-infection." (PMID 19079579, 2008). "Moreover, CR elicits lethal infection in GF Rag1-/- mice that harbor distinct host deficiencies from GF Il22-/- animals, further strengthening the notion that CR harbors gut microbiota-independent virulence." (PMID 39630719, 2024).